DNMT3B (DNA methyltransferase 3 beta)
Diseases named in the same sentence as DNMT3B in open-access papers (continued):
Sharing a sentence is not in itself a finding about the gene and the disease.
periodontitis (6 papers, 2020 to 2025). An acute or chronic inflammatory process that affects the tissues that surround and support the teeth. "Significantly higher HLA-DMB expression and its close correlation with methyltransferase DNMT3B were observed in periodontitis samples, and HLA-DMB was a promising diagnostic marker for periodontitis patients." (PMID 40267082, 2025). "The DNMT3B (rs2424913) polymorphism was associated with periodontitis and SLE alone or combined with periodontitis." (PMID 35507987, 2022). "The miR-9-1 promoter methylation yields a relative risk of 1.29 for periodontitis development, while a promoter region polymorphism in the DNMT3B causes individuals to be even 4 times more susceptible to periodontal disease." (PMID 32267380, 2020). "Both groups are in accordance with the HWE for each of the polymorphisms studied (DNMT3B (rs2424913): control, p=0.35 and periodontitis, p=0.78; MTHFR (rs1801133): control, p=0.31 and periodontitis, p=0.16)." (PMID 32267380, 2020). "For DNMT3B, the T allele and the TT genotype were detected more frequently in the periodontitis group, as well as the methylated profile on the miR-9-1 promoter region." (PMID 32267380, 2020). "For DNMT3B, the T allele was more frequent in the periodontitis (52%) compared with the control group (33%; p=0.01)." (PMID 32267380, 2020). "The polymorphism −149C→T in DNMT3B (rs2424913) and the methylated profile of the miR-9-1 promoter region are associated with periodontitis." (PMID 32267380, 2020). "In summary, the conclusion is that the genotype TT DNMT3B (rs2424913) and the methylated profile of the miR-9-1 promoter region are associated with periodontitis." (PMID 32267380, 2020). "The population studied showed the TT genotype and the T allele for DNMT3B was more frequent in individuals with periodontitis." (PMID 32267380, 2020). "Thus, aberrant DNMT3B gene expression or polymorphism would exert direct or indirect roles in periodontitis." (PMID 40267082, 2025). "Additionally, recent work has indicated that DNMT3B (rs2424913) polymorphism at the promoter region contributed to a significantly higher susceptibility to periodontitis." (PMID 40267082, 2025). "After joint analysis, we noticed that the significant association between DEG HLA-DMB and differential methyltransferase DNMT3B in periodontitis." (PMID 40267082, 2025). "Meanwhile, the role of HLA-DMB in periodontitis is probably modified by the downregulated methyltransferase DNMT3B, leading to attenuated expression-inhibition and higher HLA-DMBexpression, which jointly contributed to the progression of periodontitis." (PMID 40267082, 2025). "Next, we found that the higher expression of HLA-DMB in periodontitis PMN was probably affected by the methylation modification of DNMT3B, due to the significant correlation between them." (PMID 40267082, 2025). "This study demonstrates the association of the polymorphism -149C→T DNMT3B (rs2424913) with the occurrence of SLE and concomitant SLE + periodontitis in individuals with the inactive form of SLE." (PMID 35507987, 2022). "DNMT3B has been minimally explored in the periodontitis context and a recent study demonstrated that its expression increases after the administration of Porphyromonas gingivalis in experimental periodontitis." (PMID 32267380, 2020). "This study aims to investigate the association of polymorphisms C677T in MTHFR (rs1801133) and −149C→T in DNMT3B (rs2424913), as well as the methylation profiles of MTHFR, miR-9-1, miR-9-3, SOD1, and CAT with periodontitis." (PMID 32267380, 2020). "Whereas, aberrant DNMT3B has been rarely directly connected with periodontitis as far as we know." (PMID 40267082, 2025). "We have first revealed the correlation of DNMT3B and periodontitis PMN related genes." (PMID 40267082, 2025).
periodontitis (continued). "Therefore, the main objective of this study was to investigate the association between the MTHFR rs1801133 and the DNMT3B rs2424913 polymorphisms, and methylation profiles from MTHFR, miR-9-1, miR-9-3, superoxide dismutase (SOD1), and catalase (CAT) genes with periodontitis." (PMID 32267380, 2020). "However, the data of the study referred to the DNMT3B polymorphism rs2424913, which had not been previously studied in the periodontitis context." (PMID 32267380, 2020). "Our results showed that DNMT3B was significantly negatively correlated with GRASP, HLA-DMB, HLA-DMA, CAB39, and TLE4, implying the predominant role of DNMT3B in periodontitis." (PMID 40267082, 2025). "Compared to control samples, the methyltransferases DNMT1, DNMT2 and DNMT3B were significantly downregulated in periodontitis samples, while significantly higher DNMT3A expression was observed in periodontitis samples." (PMID 40267082, 2025). "Supporting this hypothesis, a study using ligature-induced periodontitis and Porphyromonas gingivalis gavage in C57BL/6 mice demonstrated increased DNA methyltransferase 3 beta (DNMT3b) expression in gut and maxilla tissue, as shown by the immunohistochemistry (IHC)." (PMID 40243433, 2025).
rhabdomyosarcoma (6 papers, 2016 to 2025). A rare aggressive malignant mesenchymal neoplasm arising from skeletal muscle. "The only previous study investigating the influence of DNMT3A and DNMT3B expression on radiosensitivity found a lower radiosensitivity in embryonal rhabdomyosarcoma cells in case of overexpression." (PMID 40507223, 2025). "DNMT3B, a DNA methyltransferase responsible for de novo methylation during human development, was significantly elevated in osteosarcoma and rhabdomyosarcoma." (PMID 34026613, 2021). "Likewise, another study indicated that overexpression of DNMT3B contributes to radiotherapy failure, such that its inhibition represents a promising radiosensitizing strategy for patients with metastatic or recurrent rhabdomyosarcoma tumors." (PMID 36061358, 2022). "DNMT3b was shown to be responsible for CDKI levels in human umbilical cord blood-derived stem cells, human rhabdomyosarcoma cells, and many cancer cell lines." (PMID 34571854, 2021).
adenoma (5 papers, 2008 to 2020). A neoplasm arising from the epithelium. "Our genome-wide results also confirm a selected subset of targets that was previously reported in the context of ectopic Dnmt3b expression in APCmin mice, which lead to an increase in adenoma formation." (PMID 30468428, 2018). "CD80 mRNA levels were inversely correlated with the DNMT3A mRNA levels in healthy colonic mucosa of patients with adenoma and with DNMT3B in healthy colonic mucosa of patients with cancer (τ = −0.44, p = 0.07 and τ = −0.50, p = 0.04, respectively)." (PMID 27377375, 2016). "Therefore, the global genomic methylation level and the expression DNMT3B may be involved in the stepwise progression of adenoma–carcinoma." (PMID 33061956, 2020).
autism (5 papers, 2016 to 2025). Persistent deficits in social interaction and communication and interaction as well as a markedly restricted repertoire of activity and interest as well as repetitive patterns of behavior. "Dnmt3b and cPcdh are candidate proteins involved in schizophrenia, bipolar disorder, and autism." (PMID 27912755, 2016).
colorectal tumors (5 papers, 2012 to 2021). "Higher DNMT3B levels have also been associated with the CIMP phenotype in human colorectal tumors." (PMID 23034185, 2012). "DNMT3B levels are often increased in cancers relative to normal tissues and higher levels in colorectal tumours correlate with the aberrant methylation of several CGIs12,13." (PMID 33514701, 2021). "Since the DNA methyltransferase DNMT3b plays an important role in methylation of cancer-related genes, and HOXB13 was reported to be a target gene of DNMT3b in primary colorectal tumors, we speculated that DNMT3b may also be involved in HOXB13 transcriptional repression in DU145 cells." (PMID 22808286, 2012).
COVID-19 (5 papers, 2021 to 2023). A disease caused by infection with severe acute respiratory syndrome coronavirus 2. "DNMT1, DNMT3A, and DNMT3B were inversely correlated with COVID-19 (r = -0.215, -0.528, and -0.335, respectively)." (PMID 36840831, 2023). "Analysis of an ROC curve identified both DNMT3A and DNMT3B as predictive biomarkers for COVID-19, and their combination increases their predictive power, as indicated by increasing AUC." (PMID 36840831, 2023). "Compared with the healthy COVID-19-free group, the expression of DNMT3A and DNMT3B in the blood of COVID-19 patients was decreased (P = 0.008 and 0.048, respectively)." (PMID 36840831, 2023). "On the other hand, a higher COVID-19 mortality rate in specific monogenic DNA repair defects (such as RAG1/RAG2, DNMT3B deficiencies) exists based on the current observation." (PMID 35713311, 2022). "In this study, we analyzed the expression profile of DNMTs (DNMT1, DNMT3A, DNMT3B) and HDACs (HDAC2 and HDAC3) in COVID-19 patients." (PMID 36840831, 2023). "The study revealed a pattern of decreased expression of DNMT genes (DNMT3A and DNMT3B) and an increase in the methylation of the TNF-α and TLR4 promoters in COVID-19 patients, as well as a correlation between global methylation and disease severity." (PMID 36840831, 2023). "In our study, COVID-19 patients displayed unexpected significant downregulation of DNMT3A and DNMT3B expression." (PMID 36840831, 2023). "In contrast to previous reports, DNMT3A and DNMT3B expression was found to be significantly downregulated in COVID-19 cases, whereas DNMT1, HDAC2, and HDAC3 expression did not change." (PMID 36840831, 2023). "Our data revealed that most DNA methylation changes in monocytes derived from severe COVID-19 patients occurred in genomic sites enriched in PU.1 binding motifs, consistent with earlier studies showing its role as a pioneer TF directly recruiting TET2 and DNMT3b." (PMID 36443794, 2022). "In our study, all DNMTs were inversely correlated with COVID-19 disease, whereas DNMT1 and DNMT3A, but not DNMT3B, had an inverse relationship with disease severity." (PMID 36840831, 2023). "We conducted a case-control study to investigate the differential expression of DNMT1, DNMT3A, DNMT3B, HDAC2, and HDAC3 in the blood of 120 patients (30 mild, 30 moderate, 30 severe, and 30 critical) and 30 healthy subjects without COVID-19." (PMID 36840831, 2023).
diffuse large B-cell lymphoma (5 papers, 2012 to 2025). "Prognostic analysis reveals that the expression levels of CDK6, BCL2, and DNMT3B are closely associated with the prognosis in human diffuse large B-cell lymphoma." (PMID 39864628, 2025). "Low-frequency mutations in human DNMT3B are found in hematologic malignancies including cutaneous T-cell lymphomas, hairy cell leukemia, and diffuse large B-cell lymphomas." (PMID 33450231, 2021). "More recently DNMT3B expression level has been shown to be an adverse prognosis marker in diffuse large B-cell lymphomas." (PMID 23251566, 2012). "An oncogenic role for DNMT3B is observed in several hematological cancers, including T-ALL, AML, and Burkitt and diffuse large B-cell lymphoma (DLBCL), where increased DNMT3B levels are reported to be mostly the result of increased MYC-levels." (PMID 36059621, 2022).
esophageal cancer (5 papers, 2010 to 2022). A primary or metastatic malignant neoplasm involving the esophagus. "In addition, the expression of piRNA-823 and DNMT3B were positively associated with each other, indicating that piRNA-823 might play an oncogenic function in esophageal cancer by inducing aberrant DNA methylation via DNMT3B." (PMID 35155584, 2022). "For esophageal cancer, the GeneCards database ranks CDK4 (cyclin-dependent kinase 4), DNMT3B (DNA methyltransferase 3 beta), and MAGEA4 (MAGE family member A4) as the top three relevant genes." (PMID 33273919, 2020). "The incidence of nuclear immunoreactivity of DNMT3B was significantly increased in esophageal cancer samples compared to the paired nonmalignant epithelium, which was relevant to distant metastasis as well." (PMID 35129056, 2022).
lupus (5 papers, 2013 to 2025). "Increased expression was also noted in DNMT3B (p < 0.05) in lupus patients compared to age-matched healthy controls." (PMID 23054340, 2013). "Real-time PCR analyses of DNMT1, DNMT3A and DNMT3B in peripheral blood mononuclear cells from a cohort of African American and European American lupus and non-lupus women were conducted." (PMID 23054340, 2013). "There was a significantly elevated expression of Dnmt1 and Dnmt3b, as well as Tet1 and Tet2, in CD4+ T cells of three different lupus-prone mouse strains compared to controls." (PMID 38153351, 2023).
lymph node metastasis (5 papers, 2012 to 2025). "Using univariate analysis, enhanced expressions of DNMT3b were significantly associated with a higher incidence of lymph node metastasis, a higher recurrence rate after treatment and shorter survival." (PMID 24625449, 2014). "DNMT1 expression was associated with age of the patients, menopause status, and tumor localization, while DNMT3a expression was associated with histological types and serum CA125 levels and DNMT3b expression was associated with lymph node metastasis." (PMID 22768205, 2012). "There was a positive correlation between the incidence of lymph node metastasis, disease recurrence and DNMT3b positive staining." (PMID 24625449, 2014). "Low expression of DNMT3A, low expression of DNMT3B, and locoregional lymph node metastases at presentation (N+-status) were significant significantly associated with disease-specific mortality in univariable Cox regression analysis (p = 0.029, p = 0.047, p = 0.001, respectively)." (PMID 40507223, 2025). "DNMT3a expression was positively associated with serum CA125 level, while DNMT3b expression was associated with lymph node metastasis and serum CA199 level, which is novel and was not report before." (PMID 22768205, 2012).
renal cell carcinoma (5 papers, 2017 to 2023). "In order to determine the functions of DNA methyltransferase in kidney tumorigenesis on the molecular level, we examined the mRNA expression levels of DNMT1, DNMT3A, DNMT3B, and DNMT3B variants in renal cell carcinoma tissue." (PMID 28160561, 2017). "Both mRNA and protein levels of DNMT3B4, a splice variant of DNMT3B, were increased in renal cell carcinoma tissue compared with adjacent control tissues." (PMID 28160561, 2017). "Moreover, DNMT3B expression has been associated with vascular invasion in sporadic human renal cell carcinoma, further suggesting the role of DNMT3B in tumor invasion." (PMID 37367043, 2023).
schizophrenia (5 papers, 2014 to 2023). A major psychotic disorder characterized by abnormalities in the perception or expression of reality. "Recent case–control studies indicated a significant association between minor alleles of DNMT1 (rs2114724 and rs2228611), DNMT3B (rs2424932 and rs1569686) and susceptibility of schizophrenia, while it is rare." (PMID 37833704, 2023). "This study investigated the genotype and allele distribution of DNMT1 (rs2114724 and rs2228611) and DNMT3B (rs1569686, rs2424908, rs2424932, and rs6119954) in 134 patients with schizophrenia and 64 healthy controls." (PMID 37833704, 2023). "Recently, it was reported that DNMT3B rs2424932 was strongly associated with gender and DNMT3B rs1569686 associated early age onset of schizophrenia while DNMT3L rs2070565 associated with family history and early onset of schizophrenia." (PMID 35832186, 2022). "The genetic variants in DNMT1, rs2114724 and rs2228611, were found to be significantly associated with schizophrenia while de novo DNMTs variants, DNMT3B rs2424932, DNMT3B rs156968, and DNMT3L rs2070565, were associated with early age onset of disease." (PMID 27314012, 2016). "In our study, we report an association of DNMT3B rs1569686 TT genotype and T allele with early onset of schizophrenia." (PMID 24859147, 2014). "Stratifying the patients based on their genotypes and demographic variables we observe a strong association of DNMT3B rs2424932 GG genotype and G allele with schizophrenia in male patients." (PMID 24859147, 2014). "DNMT3B rs2424932 GG genotype (P = 0.023) and G allele (P = 0.0063) was found to be associated with the Schizophrenia in male patients when compared against male controls." (PMID 24859147, 2014). "DNMT3B rs1569686 (genotype P = 0.027, allele P = 0.033) was found to be associated with early onset of schizophrenia and also with family history and early onset (genotype P = 0.009)." (PMID 24859147, 2014). "In the subgroup analysis with age of onset and family history we found that DNMT3B rs1569686 was associated with genotypic (P = 0.027) and allelic (P = 0.033) level with an overrepresentation of TT genotype and T allele in patients with early onset of Schizophrenia." (PMID 24859147, 2014). "We examined the haplotype distribution of DNMT1 (rs2114724 and rs2228611) and DNMT3B (rs1569686, rs2424908, rs2424932, and rs6119954) in both the schizophrenia and control groups." (PMID 37833704, 2023). "Recently, a south Indian population was studied for genetic polymorphism in DNMT1, DNMT3A, DNMT3B, and DNMT3L for association with schizophrenia." (PMID 27314012, 2016). "Association analysis of DNMT1, DNMT3A, DNMT3B and DNMT3L polymorphisms are summarised by -Log P value for schizophrenia in a South Indian population." (PMID 24859147, 2014). "We screened for polymorphisms in DNA methyltransferases, DNMT1, DNMT3A, DNMT3B and DNMT3L in 330 schizophrenia patients and 302 healthy controls for association with Schizophrenia in south Indian population." (PMID 24859147, 2014). "Observations from association analyses of SNPs in DNMT1, DNMT3A, DNMT3B, and DNMT3L indicated that DNMT1 rs2114724 and rs2228611 were strongly associated with schizophrenia at allelic and genotypic level." (PMID 24859147, 2014). "DNMT3B rs2424932 genotype (P = 0.023) and allele (P = 0.0063) increased the risk of developing schizophrenia in males but not in females." (PMID 24859147, 2014). "None of the selected SNPs in DNMT3B, and DNMT3L were found to be associated with schizophrenia." (PMID 24859147, 2014).
T cell lymphomas (5 papers, 2012 to 2021). "On the molecular level, DNMT3B-deficient T-cell lymphomas had increased genomic instability, a global decrease of 5-methylcytosine levels, e.g. on short interspersed nuclear elements (SINE)." (PMID 22563479, 2012). "This is further supported by methylation data from MYC-induced T-cell lymphomas with modulated Dnmt3b activities in which AF seemed to substantially suppress loss of methylation." (PMID 33450231, 2021). "We show that 43% of Dnmt3b+/− mice developed T-cell lymphomas, chronic lymphocytic leukemia, and myeloproliferation over 18 months, thus resembling phenotypes previously observed in Dnmt3a+/− mice, possibly through regulation of shared target genes." (PMID 33450231, 2021). "Taken together, the expression analysis indicates a direct correlation between MYC and DNMT3B expression levels in human B- and T-cell lymphoma." (PMID 29100357, 2017). "Similarly to our previous study of Dnmt3a+/− mice, our data identify Dnmt3b as a haploinsufficient tumor suppressor in T-cell lymphomas (TCL) and CLL." (PMID 33450231, 2021). "In addition, Dnmt1 was shown to have cancer-specific de novo activity in a mouse model of MYC-induced T cell lymphomas, whereas Dnmt3a and Dnmt3b were primarily involved in maintenance methylation in tumors." (PMID 27690235, 2016). "In particular, in our previous studies we observed upregulation of Dnmt3b in Dnmt3a-defficient MYC-induced T cell lymphomas, suggesting that such an event may result in aberrant de novo methylation." (PMID 27690235, 2016).